CD44 (CD44 molecule (IN blood group))
Diseases named in the same sentence as CD44 in open-access papers (continued):
Sharing a sentence is not in itself a finding about the gene and the disease.
gastric cancer (continued). "Inhibition of proliferation and migration of gastric cancer cells after CD44 knockdown was observed." (PMID 36316684, 2022). "In conclusion, the analysis results of mRNA and protein levels showed that CD44 expression was upregulated in gastric cancer, which was different from that in normal tissues." (PMID 36316684, 2022). "MKN45 cells were reported to be more stem-cell-oriented (i.e., CD44 positive) in nature than other gastric cancer cells." (PMID 36010879, 2022). "The relative expression level of CD44 RNA in gastric cancer was analysed in the TCGA and GEPIA2 databases and validated in the GEO database." (PMID 36316684, 2022). "This study has further improved our understanding of the relationship between CD44 and gastric cancer." (PMID 36316684, 2022). "The expression of CagA is significantly higher in CD44 positive gastric cancer cells, mainly because CD44 positive gastric cancer stem cells can inhibit autophagy and further increase the expression level of CagA." (PMID 35463631, 2022). "Our study further solidifies the key role of CD44 in gastric cancer and reveals its close relationship with prognosis and immune infiltration, suggesting that CD44 can be used as an exact target for the diagnosis and treatment of gastric cancer." (PMID 36316684, 2022). "The Human Protein Atlas (HPA) database was used to analyse the differential expression of CD44 protein in gastric cancer and normal tissues." (PMID 36316684, 2022). "It was found that CD44 was significantly correlated with all three, which proved that CD44 plays an indispensable role in the immune microenvironment of gastric cancer." (PMID 36316684, 2022). "CD44 is also a candidate marker for gastric cancer stem cells 47, and more importantly, deletion of CD44 suppressed gastric cancer progression in a transgenic mouse model." (PMID 35864961, 2022). "It is positively correlated with CD44 and plays a synergistic role in the carcinogenesis of gastric cancer." (PMID 36316684, 2022). "Based on sex, CD44 expression was significantly increased in both male and female gastric cancer patients compared with the normal control group." (PMID 36316684, 2022). "To determine the role of CD44 in the proliferation and migration of gastric cancer cells, we used siRNA to knock down CD44 in SGC7901 and MGC803 cells." (PMID 36316684, 2022). "The results showed that CD44 was highly expressed in the gastric cancer samples (n = 373) compared with the normal adjacent tissue samples (n = 32) and that there were significant differences (P = 0.0374 < 0.05)." (PMID 36316684, 2022). "The effect of CD44 on the proliferation and migration of gastric cancer cells was detected by CCK8 and transwell assays." (PMID 36316684, 2022). "In gastric cancer, CD44 regulates stem cell proliferation by increasing cyclin D1 expression, and the expressions of CD44 and cyclin D1 are positively correlated with tumor differentiation." (PMID 36042265, 2022). "Similar results had been observed in paclitaxel-resistant gastric cancer cells that paclitaxel enriched CD44 population accompanied with EMT." (PMID 35931675, 2022). "Accordingly, the enhanced TRAIL susceptibility of the spheroid-cultured gastric cancer cells seems to be associated with a tendency of CD44 upregulation and an increased expression of DR4 and DR5 upon the spheroid culture of the gastric cancer cells." (PMID 36661504, 2022). "Differences in CD44 between gastric cancer cell lines and normal cells were detected by real-time PCR, and the HPA database was used to analyse the differential expression of CD44 protein in gastric cancer and normal tissues." (PMID 36316684, 2022). "Studies have confirmed that the expression of SALL4 and CD44 is also positively correlated in gastric cancer cells." (PMID 36316684, 2022). "CD44 can be used as an immune checkpoint to evaluate the prognosis of gastric cancer, which can improve the prognostic accuracy of gastric cancer patients." (PMID 36316684, 2022).
gastric cancer (continued). "For example, the circFNDC3B regulates and increases the stability of CD44 expression by forming a ternary complex of circFNDC3B/IGF2BP3/CD44 mRNA, subsequently promoting cell invasion and migration of gastric cancer cells." (PMID 34944493, 2021). "HA and AHNP on the nanoparticle surface allowed superior delivery of SN38 to gastric cancer cells by targeting CD44 and HER2, leading to repressed relative signalling cascades and inhibition of cell growth and invasion." (PMID 34944493, 2021). "After sorting for the CSC-associated surface marker CD44 in vitro, the expressions of miR-106b and miR-196a-5p were observed to be upregulated in comparison to CD44- gastric cancer cells." (PMID 33562727, 2021). "It has been reported that circFNDC3B contributes to the invasion and migration by modulating CD44 and E-cadherin expression in gastric cancer cells." (PMID 34434890, 2021). "The presence of HA-coated and CD44+ TEVs has been detected after their release by gastric cancer cells." (PMID 33540535, 2021). "CD44+ gastric cancer cell populations have been found to exhibit characteristics of CSCs, such as self-renewal, spheroid colony formation, and tumorgenicity in vivo." (PMID 33562727, 2021). "CD44 is another marker used to isolate a number of different CSCs lineages, such as colon, prostate, pancreatic and gastric cancer." (PMID 34066147, 2021). "In gastric cancer, CD44 and HER2 are considered key molecules that participate in many crucial cellular processes." (PMID 34944493, 2021). "Increasing evidence also suggests that CD44 is extensively overexpressed in other cancer types including gallbladder, prostate, ovarian, oral squamous cell carcinoma and gastric cancer, correlating with aggressive biological behaviour and a poor prognosis." (PMID 34944493, 2021). "CD44 has been reported to be present on TEVs derived from gastric cancer cell lines, ovarian, pancreatic, and primary mesenchymal cells." (PMID 33540535, 2021). "The cooperative interaction of FGFR2 and CD44 maintains gastric cancer stemness via reciprocally regulating their expression by differentially regulating c-Myc transcription." (PMID 34944493, 2021). "PLGA nanoparticles modified with polyethylene glycol and conjugated with an engineered anti-human CD44v6 Fab (AbD15179) were developed to specifically target human CD44 isoforms containing exon v6 (CD44v6) present in stomach cancer cells." (PMID 35423427, 2021). "A recent study showed that Chi3l1 was upregulated during gastric cancer (GC) development and that through binding to CD44, it activated Erk, Akt, and β-catenin signaling, thereby enhancing GC metastasis." (PMID 34110284, 2021). "CD44+ circulating tumour cells (CTCs) in patients with gastric cancer were also shown to correlate with the clinicopathologic characteristics of the resected tumour specimens, including disease stage and venous invasion, whilst CD44− CTCs did not." (PMID 33628765, 2021). "CD44-mediated gastric cancer cell invasion and metastasis by binding to human epidermal growth factor receptor 2 (HER2) inhibits miR-139 and upregulates the miR-139 target gene, C-X-C chemokine receptor type 4 (CXCR4)." (PMID 34944493, 2021). "The current results were in line with those of other studies on cancer of other organs and increased expression of CD44 from normal mucosa to dysplasia and cancer has been previously reported in esophageal and gastric cancers." (PMID 33681421, 2021). "HOXC9 has been suggested to promote the CSC phenotype in gastric cancer cells in vitro, as observed by the downregulation of CSC-associated surface markers CD44 and EpCAM, and CSC-associated markers SOX2 and OCT-4, after the knockdown of HOXC9." (PMID 33562727, 2021). "It is apparent that stem cell markers Oct3/4, Sox2 and CD44 maintain the stemness of gastric cancer in tumorsphere cells." (PMID 32160650, 2020).
gastric cancer (continued). "Chen and coworkers employed PLGA-Lecithin-PEG Nanoparticles (PLPNs) conjugated with both antibodies against CD44 and CD133 and loaded with ATRA (CD44/CD133-ATRA-PLPNs) to target two different populations of gastric cancer stem cells." (PMID 32731612, 2020). "H. pylori-infected (CagA-positive) gastric cancer cells exhibit CSC properties via increased expression of surface markers—CD44 and Lgr5 with Nanog, Oct4, and c-myc upregulation." (PMID 32340207, 2020). "SLC7A11 combined with CD44 (cancer cell stem marker) controls the reduced glutathione and defense against reactive oxygen species in a transgenic mouse model of gastric cancer." (PMID 33362856, 2020). "The expression of DAXX inversely correlates with that of cancer stem cell markers CD44 and Oct4 in gastric cancer lines." (PMID 32203224, 2020). "Surface markers of gastric cancer stem cells CD133 and CD44 were found to be significantly decreased in the SGC-7901 gastric cancer cell line following GDC-0499 treatment." (PMID 31979397, 2020). "Takaishi proved that the CD44 (+) gastric cancer stem cells were more resistant to 5-fluorouracil (5-FU), etoposide (VP-16) and radiation than the CD44 (-) gastric cancer cells." (PMID 32788883, 2020). "It has been observed that osteopontin expression is correlated with CD44 level in lung small cell lung cancer and gastric cancer." (PMID 33303029, 2020). "The relevance of the infection by CagA-positive H. pylori strain on EMT in gastric cancer was confirmed by significantly higher expression of CD44 and mesenchymal markers in tumor samples." (PMID 32340207, 2020). "Wang 32 found that abnormal expression of CD44 in gastric cancer tissues suggesting a poorer prognosis, this was consistent with our research." (PMID 32788883, 2020). "The cell-surface transmembrane glycoprotein CD44 binds to the extracellular domain of hyaluronic acid (HA), and is overexpressed in breast, ovarian, lung, and stomach cancer." (PMID 32982750, 2020). "According to the studies, CD44 is one of the most common markers of cancer stem cells (CSCs) in gastric cancer, which has the potential for regeneration, initiation of tumor progression, and possibly development of metastasis." (PMID 32592354, 2020). "Cases of gastric cancer with CD44+ in CK+ epithelial CTCs are significantly more common among patients with distant metastases and associated with shorter survival than that observed in the case of patients with CK+CD44− CTCs." (PMID 33266262, 2020). "We further showed that knockdown of DAXX in gastric cancer cells sustains cell survival, enhances the expression of stem cell markers CD44 and Oct4 and promotes tumour growth." (PMID 32203224, 2020). "CD44+ phenotype of cytokeratin-positive cells in blood and bone marrow is an independent prognostic factor in patients with gastric cancer." (PMID 30056567, 2019). "The TGF-β-SMAD signaling is involved in modulating the cancer stem cell-like properties of CD44-positive gastric cancer cells, hepatocellular carcinoma cells, and cervical cancer cells." (PMID 31619018, 2019). "-Both CD44 and EpCAM markers are needed for isolation of cancer stem cells directly from patients. -In addition to in vivo experiments, gastric cancer stem cells generate various differentiated cells in cancer sphere culture." (PMID 31024835, 2019). "Very fascinatingly, we found that upregulation of HOXA11 in gastric cancer cells resulted in increased expression of cancer stem cell factors such as CD44, CD90, CD133 and Bmi1 as well as pluripotency markers Nanog and Sox2 and vice versa." (PMID 31695791, 2019). "In the present study, after treatment with 5-FU in the presence of GCAFs, the percentage of CD44+/CD24− gastric cancer cells was significantly elevated in the GCAF-sh group." (PMID 31139014, 2019). "The lymphocyte homing receptor CD44 was proposed as a marker for cancer stem cells of many solid malignancies, including gastric cancer." (PMID 30056567, 2019).
gastric cancer (continued). "Immunohistochemistry assay were performed to examine the cancer stem cell markers in primary gastric cancer and peritoneal foci, we found that CD44 is highly expressed in both sites, and the expression is strongly positive in peritoneal ones especially." (PMID 31695791, 2019). "The transmembrane glycoprotein CD44 was one of the first molecules identified on gastric cancer stem cells." (PMID 30056567, 2019). "Two independent studies demonstrated that CD44+ CTCs isolated from peripheral blood of gastric cancer patients were able to induce tumors when injected into immunodeficient mice." (PMID 30056567, 2019). "This study was focused on standard form of CD44 and its effect on morphology, malignant potential, HA metabolism and EV secretion of gastric carcinoma cells." (PMID 30909497, 2019). "We immobilized HA with different molecular weights (Mw) in a Layer-by-Layer (LbL) fashion and studied the interactions of the substrates with CD44 and two human gastric cancer cell lines that overexpress this receptor, namely AGS and MKN45." (PMID 30375477, 2018). "It was also reported that MKN-45, MKN-74, and NCI-N87 gastric cancer cell lines contain a considerable number of CD44-positive cells." (PMID 29422082, 2018). "In gastric cancer, CD44+ cells show upregulation of HH pathway proteins and HH inhibition by Smoothened (Smo) shRNA decreases spheroid and colony formation, migration, invasion, and anchorage-independent growth." (PMID 30211160, 2018). "We chose a set of genes that were reported to encode gastric cancer stem cell markers such as LGR5, CD133, CD44, CD54, ABCG2 and MSI1, and then performed qPCR to detect their expression in both NANOGP8-transfected (SGC7901-NANOGP8) and mock cells (SGC7901-NC)." (PMID 29689047, 2018). "In the CD44+ gastric cancer stem-like cells, the entire cluster was significantly upregulated and inhibition of miR-106b led to a decreased self-renewal capacity and cell invasiveness through the suppression of the TGF-β/Smad signaling pathway." (PMID 29434344, 2018). "Here, a CSC-like cell population with a high level of CD44 expression was obtained from the human gastric cancer cell lines MKN45 and MKN74." (PMID 28430578, 2017). "The hyaluronic acid receptor, CD44, has various isoforms generated by alternative splicing, and some isoforms are known to be correlated to gastric cancer." (PMID 28694503, 2017). "Notch1 is considered a potential target of bELE because CD44+ gastric cancer stem‐like cells proliferate faster than their CD44− counterparts and express a higher level of Notch1." (PMID 28297578, 2017). "In order to assess whether CD44 protein expression was due to alteration in CD44 genotypes, we further analyzed the association of genotype patterns and protein expression of CD44 in patients with chronic gastritis, precancerous gastric lesions and gastric cancer." (PMID 29445738, 2017). "In this study, to find out the most appropriate CD44v for targeting AGC, we analysed the expression differences of CD44 isoforms at the mRNA level in stomach cancer cell lines as well as in 74 patients with AGC by using exon-specific qRT-PCR." (PMID 28694503, 2017). "Targeting CD44-positive cells should be tested in gastric cancer animal model to evaluate its therapeutic potential for cancer." (PMID 29212456, 2017). "In gastric cancer, 69 cases of positive CD44 protein expression carried AG genotype (35.89%) and 89 cases carried GG genotype (43.58%) whereas 4 cases carried AA genotype (2.56%)." (PMID 29445738, 2017). "CD44 expression has also been reported in gastric cancer and has been suggested as a useful predictive marker in patients with gastric cancer." (PMID 29445738, 2017). "CD44 has been suggested to represent an important prognostic marker for various cancer types including gastric cancer with its elevated expression." (PMID 29445738, 2017).
gastric cancer (continued). "During carcinogenesis, expression of the standard CD44 form is up-regulated in various carcinomas including breast, ovarian, colon, lung and stomach cancer." (PMID 28212584, 2017). "Although the roles of CD44v in cancer stem cells (CSCs) remain elusive, it was reported that CD44(+) gastric cancer cells have the stem cell properties of self-regeneration and the ability to form differentiated programs when compared with CD44(−) cells." (PMID 28694503, 2017). "CD44 cleavage, shedding, and elevated levels of soluble CD44 in the serum of patients is a marker of tumor burden and metastasis in several cancers including colon and gastric cancer." (PMID 28326306, 2017). "We analyzed the expression levels of the CD44 protein using immunohistochemistry of 300 patients with chronic gastritis, precancerous gastric lesions, and gastric cancer." (PMID 29445738, 2017). "Multiple carcinomas including breast, ovarian, colon, lung and stomach cancer, overexpress the hyaluronic acid (HA) receptor, CD44." (PMID 28212584, 2017). "In gastric cancer cells, especially cancer stem cells (CSCs), miR-145 regulates CD44 by directly targeting the CD44 3′-untranslated region (3′-UTR)." (PMID 28832500, 2017). "To quantify the CD44 molecules on the cell surface, we performed immunocytochemistry of three gastric cancer cells (MKN-28, KATO-III, and SNU-638) and normal cells (HDF) to compare the protein expression with the expression level of mRNA." (PMID 28694503, 2017). "They found that CD44 expression was related to stage, tumor size, and lymph node metastasis of gastric cancer, whereas CD44v6 was related to lymph node metastasis, lymphatic invasion, and venous invasion." (PMID 28512631, 2017). "For instance, GAPLINC improve CD44 expression by competing for miR-211-3p, subsequently mediating cell migration and proliferation in gastric carcinoma." (PMID 28404901, 2017). "Positivity of RP-1 staining was observed in 73 gastric carcinoma tissue samples and 10 surrounding tissue samples, and positivity of anti-CD44 antibody in 64 gastric carcinoma samples and 15 surrounding tissue samples." (PMID 28415792, 2017). "In RP-1 and anti-CD44 antibody IHC staining of gastric carcinomas and surrounding tissues, immunoreactivities were observed both on cell membrane and in cytoplasm." (PMID 28415792, 2017). "Clinical studies demonstrated that the expression of SALL4 and CD44 was positively correlated in gastric cancer patient samples." (PMID 27819668, 2016). "More importantly, YM155 inhibited CD44 expression in gastric cancer cells and gastric cancer tissues both in vitro and in vivo." (PMID 26771139, 2016). "Here, we show that the transcription of a long non-coding RNA (lncRNA), Gastric Adenocarcinoma Associated, Positive CD44 Regulator, Long Intergenic Non-Coding RNA (GAPLINC), is directly activated by HIF-1α in gastric cancer (GC)." (PMID 27729869, 2016). "CD44+ gastric cancer cells is a CSC marker of human gastric cancer and have stronger tumorigenic than CD44− gastric cancer cells." (PMID 26771139, 2016). "We then performed a chromatin immunoprecipitation assay to test the binding of SALL4 protein to CD44 promoter in gastric cancer cells." (PMID 27819668, 2016). "The results of cell counting assay showed that SALL4 knockdown decreased the growth of gastric cancer cells while CD44 overexpression significantly increased the growth of gastric cancer cells." (PMID 27819668, 2016). "Opposite roles of CD44 mRNA were also found in well-differentiated gastric cancer and poorly/moderately differentiated gastric cancer." (PMID 27323782, 2016). "In our study, higher CD44 mRNA was identified in both colon and gastric cancer by using TCGA database." (PMID 27323782, 2016). "Similar to the results of prognostic analysis for overall survival, CD44, Shh, and Gli1 status also affected the recurrence of gastric cancer in our study." (PMID 26839535, 2016).